KLF5 (KLF transcription factor 5)
Diseases named in the same sentence as KLF5 in open-access papers (continued):
Sharing a sentence is not in itself a finding about the gene and the disease.
bladder cancer (continued). "Therefore, we proposed a hypothesis that KLF5 could be an important target of curcumin in bladder cancer cells." (PMID 25170806, 2014). "Validation through in vitro experiments confirmed that KLF5 is upregulated in glioblastoma (GBM) and bladder cancer, and that its knockdown effectively suppresses GBM and bladder cancer growth." (PMID 41583492, 2025). "On the other hand, the protein levels of KLF5 and VEGFA are correlated with the expression of CD31, a marker of neovascularization, in human bladder cancer tissues and tumor xenografts in nude mice." (PMID 26544730, 2015). "Our data here not only elucidate the mechanism how KLF5 activates the transcription of VEGFA, but also provide evidence of the correlation between expression of KLF5 and VEGFA in human bladder cancer cell lines and tissues." (PMID 26544730, 2015). "Taken together, our results indicate that KLF5 promotes angiogenesis of bladder cancer through directly regulating VEGFA transcription and suggest that KLF5 could be a novel therapeutic target for angiogenesis inhibition in bladder cancer." (PMID 26544730, 2015). "In addition, there was a positive correlation between KLF5 and VEGFA expression in human bladder cancer tissues by immunohistochemistry assay and statistical analysis from TCGA and GEO data." (PMID 26544730, 2015). "The mRNA level of WWP1, FBW7 and SMURF2, which have been reported to interact with KLF5 and mediate the ubiquitination of KLF5, were not significantly up-regulated by curcumin in 5637 and WH bladder cancer cells." (PMID 25170806, 2014). "In this study, we demonstrated that curcumin targeted KLF5 by promoting its proteasome degradation, but not by inhibiting its transcription in bladder cancer cells." (PMID 25170806, 2014). "Moreover, exogenous KLF5 expression increased cell cycle transition and up-regulated cyclin D1 in TSU-Pr1 human bladder cancer cells." (PMID 25170806, 2014). "Interestingly, both amplification and deletion of KLF5 could be found at a similar rate in some cancer types, such as uterine carcinosarcoma (UCS) and bladder cancer (BLCA)." (PMID 33923166, 2021). "Moreover, suppression of KLF5-VEGFA axis by the inhibitors of upstream oncogenic signaling pathways (such as RTKs and PI3K) and inhibitor of KLF5 suggested KLF5 as a potential therapeutic target in bladder cancer." (PMID 26544730, 2015). "Therefore, KLF5-VEGFA axis could be regulated by RTKs/RAS/MAPK and PI3K/Akt pathways, which might provide a novel therapeutic target in bladder cancer." (PMID 26544730, 2015). "Thus, inhibition of KLF5 could avoid the bypass of different pathways and it could be a better strategy to suppress VEGFA in bladder cancer." (PMID 26544730, 2015). "Growth factors (EGF and bFGF) and stimuli (PMA and LPA) that activated downstream oncogenic signaling (such as PKC, MEK/Erk and PI3K/Akt) could elevate the expression of KLF5, then increased VEGFA transcriptional efficiency and promoted bladder cancer angiogenesis." (PMID 26544730, 2015). "Furthermore, we found that two pivotal pathways in bladder cancer, RTKs/RAS/MAPK and PI3K/Akt, might convey their oncogenic signaling through KLF5-VEGFA axis." (PMID 26544730, 2015). "Moreover, at both mRNA level (TCGA and GEO data) and protein level (IHC staining), KLF5 and VEGFA were found to be co-expressed in human bladder cancer tissues, further supporting that KLF5 could be an essential regulator of VEGFA in bladder cancer." (PMID 26544730, 2015). "Furthermore, CID 5951923, a specific KLF5 transcriptional inhibitor identified by cell-based ultrahigh-throughput screening, abolished KLF5 and VEGFA expression in 5637 and WH bladder cancer cells, suggesting potential application of KLF5 inhibitor in bladder cancer treatment." (PMID 26544730, 2015). "In non-tumor urothelial cell line SVHUC and six bladder cancer cell lines, RT4, WH and 5637 cells were found to express relatively high level of KLF5 protein and mRNA." (PMID 26544730, 2015).
pancreatic cancer (28 papers, 2013 to 2026). "Within this signature, MR provided suggestive evidence for a modest association between genetically predicted Krüppel-like factor 5 (KLF5) expression and pancreatic cancer risk (OR = 1.188, p = 0.046)." (PMID 41727317, 2026). "Numerous studies reported association-specific genome loci, including KLF5 and pancreatic cancer risk." (PMID 37239940, 2023). "An analysis of 8000 genotyped PanC4 individuals found that KLF5 was strongly associated with pancreatic cancer." (PMID 37239940, 2023). "GWAS have also identified a pancreatic cancer risk locus in the region between KLF5 and KLF12 (refs 34, 35, 36)." (PMID 27117709, 2016). "In conclusion, our study indicated that repression of KLF5 could render BRCA1-proficient pancreatic cancer cells BRCA1 deficiency and thus sensitized them to PARP inhibition." (PMID 38433576, 2024). "High expression of KLF5 is associated with poor survival in colorectal and pancreatic cancers." (PMID 37377893, 2023). "To determine whether KLF5 could be used as a prognostic biomarker in patients with pancreatic cancer, we built the risk score model described in the Methods section." (PMID 31327760, 2019). "Correspondingly, TCGA and GTEx data also indicated that KLF5 was highly expressed in pancreatic cancer." (PMID 39827156, 2025). "Ablation of KLF5 in pancreatic cancer cells can alter the tumor immune microenvironment and sensitize tumors cells to combination immunotherapy." (PMID 39827156, 2025). "Eventually, inhibition of KLF5 potentiated the cytotoxic effect of oxaliplatin in pancreatic cancer." (PMID 39827156, 2025). "Here, the authors discover that RUVBL1/2 regulation of KLF5 modulates both classical and basal-like transcriptional lineage programs in pancreatic cancer." (PMID 41241675, 2025). "We further examined the expression and prognostic significance of KLF5 in the top ten cancers with the highest mortality rates, in addition to pancreatic cancer." (PMID 39827156, 2025). "Survival analysis showed that OS and DFS were significantly shorter in pancreatic cancer patients with high KLF5 expression." (PMID 39827156, 2025). "Emerging evidence has also revealed that KLF5 drives the progression of pancreatic cancer by inducing proliferation, glycolysis, and immunosuppression [13‒15]." (PMID 38433576, 2024). "In the present study, we explored the potential role of KLF5 in sensitivity to PARP inhibitors in pancreatic cancer cells." (PMID 38433576, 2024). "Based on the significant correlation between high expression of KLF5 and poor prognosis of pancreatic cancer, the vital role of KLF5 as a substrate of FBW7 was indicated by our previous study." (PMID 38433576, 2024). "In one study that functionally screened for pancreatic cancer gene candidates, KLF5 transcript levels were locally amplified in pancreatic cancer cell lines." (PMID 37239940, 2023). "Further analysis of low- and high-grade tumors and pancreatic cancer cell lines obtained from PDAC patients demonstrated that KLF5 was explicitly expressed in low-grade PDAC." (PMID 37239940, 2023). "A comprehensive evaluation of the effects of KLF5 knockdown and overexpression in pancreatic cancer cell lines led to the identification of genes directly regulated by this TF." (PMID 37239940, 2023). "Bone-derived TGF-β also acetylates KLF5, a transcription factor, in pancreatic cancer-related bone metastasis, and following its acetylation, KLF5 activates CXCR4 to induce osteoclast differentiation, thereby leading to IL-11 secretion." (PMID 38352248, 2023). "Using human pancreatic cancer tissues, others show that KLF5 is significantly increased in cancer tissues compared to the normal adjacent pancreas." (PMID 37239940, 2023). "In pancreatic cancer, KLF5 has been shown to be overexpressed and to facilitate cell growth and survival." (PMID 37461162, 2023).
pancreatic cancer (continued). "Another way that KLF5 promotes glycolysis of pancreatic cancer is through transcriptional activation of phospholipase A and acyltransferase 3 (PLA2G16)." (PMID 37239940, 2023). "Here, we describe the mechanisms regulating KLF5 expression in pancreatic cancer and their significance on its function at different stages of PDAC." (PMID 37239940, 2023). "Knockdown of KLF5 in pancreatic cancer cell lines led to cell cycle arrest at the G1 phase, inhibiting cell DNA replication and division." (PMID 37239940, 2023). "The over-expressed KLF5 directly inhibits p16 expression in pancreatic cancer to promote the G1/S phase transition of cancer cells." (PMID 36761967, 2023). "Among others, KLF5 has been amplified in pancreatic cancer, and its knockdown decreases the proliferation of pancreatic cancer cells." (PMID 37239940, 2023). "Klf5 TF is highly expressed in human pancreatic cancer and is also expressed in normal pancreatic ductal cells and alveolar-to-ductal metaplasia (ADM)." (PMID 35965507, 2022). "KLF5 overexpression has been previously identified in a wide variety of cancers, including lung cancer, cervical cancer, thyroid cancer, pancreatic cancer, and melanoma 42-46." (PMID 35154481, 2022). "Kruppel-like factor 5 (KLF5) is commonly upregulated in several cancer types and promotes pancreatic cancer proliferation by targeting the cell cycle." (PMID 34367349, 2021). "Conversely, in the absence of Smad4, survival and tumor propagation are ensured in pancreatic carcinoma cells; Snail is repressed instead of Klf5, leading to cooperation between Klf5 and Sox4 to prevent apoptosis." (PMID 34298613, 2021). "While in most cancer cells, TGFβ-induced EMT is associated with pro-oncogenic response, in pancreatic cancer cells with an intact TGFβ/SMAD4 pathway, it was found associated with apoptosis in a KLF5 repression-dependent manner." (PMID 31822964, 2020). "In summary, we found that levels of KLF5 are higher in tissue samples from short-surviving pancreatic cancer patients than in samples from long-surviving patients." (PMID 31327760, 2019). "Collectively, these findings demonstrate that KLF5 is an important prognostic biomarker in pancreatic cancer patients, and they shed light on the molecular mechanism by which KLF5 stimulates cell cycle progression in pancreatic cancer." (PMID 31327760, 2019). "To investigate the mechanism by which high KLF5 expression leads to a poorer prognosis in pancreatic cancer patients, we examined the important genes activated or inhibited by KLF5 in the pancreatic cancer pathway extracted in the KEGG." (PMID 31327760, 2019). "The KLF5 expression level thus appears to be a prognotic biomarker in patients with pancreatic cancer." (PMID 31327760, 2019). "In the present study, we used data from The Cancer Genome Atlas (TCGA) and an mRNA array to confirm that KLF5 expression is a key determinant of survival time in pancreatic cancer patients after surgery as well as a prognostic biomarker in pancreatic cancer." (PMID 31327760, 2019). "In that study, KLF5 was knocked out in the CFPAC-1 pancreatic cancer cell line using CRISPR/Cas9-mediated genome editing." (PMID 31327760, 2019). "In the present study, mRNA array and immunohistochemical analyses showed that KLF5 is highly expressed in tissue samples from three short-surviving patients with pancreatic cancer." (PMID 31327760, 2019). "To determine the regulatory relationships between KLF5 and its target genes, we initially compared the levels of KLF5 expression between four pancreatic cancer cell lines (PANC-1, BxPC-3, CFPAC-1, and SW1990) and a line of normal pancreatic cells (HPDE6C7)." (PMID 31327760, 2019). "In pancreatic cancer, a recent study showed that KLF5 promotes cell proliferation, acinar-to-ductal metaplasia, pancreatic intraepithelial neoplasia, and tumor growth." (PMID 31327760, 2019).
pancreatic cancer (continued). "Most notably, the analysis also revealed novel possible oncogenic functions of nucleoporin NUP153 (ostensibly by modulating TGFβ signaling) and Kruppel-like transcription factor KLF5 in pancreatic cancer." (PMID 24041470, 2013). "Moreover, we reanalyzed the transcriptome sequencing in which KLF5 was knocked out in pancreatic cancer cell line CFPAC-1." (PMID 39827156, 2025). "These indicated that inhibition of KLF5 enhanced ferroptosis in pancreatic cancer cells." (PMID 39827156, 2025). "Interestingly, TF activity analysis showed that Ep_VGLL1 can be distinguished by the high activities of KLF5 and SOX4, the TF pair marking the tumorigenic SMAD4-deficient pancreatic cancer cells under the TGF-β milieu." (PMID 38297291, 2024). "Our present results suggested that repression of KLF5 promoted olaparib-induced DNA damage in pancreatic cancer cells and increased olaparib sensitivity by suppressing the transcription of BRCA1, which could be reversed by upregulation of BRCA1." (PMID 38433576, 2024). "Since the cooperation between SOX4 and KLF5 has been suggested as a molecular mechanism that drives tumorigenesis in SMAD4 defect pancreatic cancer cells, we postulated that Ep_VGLL1 represents cancer cells in SMAD4-deficient oncogenic processes driven by TGF-β." (PMID 38297291, 2024). "To investigate whether KLF5 could decrease the IC50 of PARP inhibitors in pancreatic cancer cells, we examined the viability of cells cultured in olaparib at gradient concentrations." (PMID 38433576, 2024). "Our results indicate that inhibition of KLF5 may induce BRCAness in a larger pancreatic cancer subset with proficient BRCA." (PMID 38433576, 2024). "Furthermore, olaparib combined with an inhibitor of KLF5 showed stronger cytotoxicity to pancreatic cancer cells." (PMID 38433576, 2024). "A recent study demonstrated that Klf5 loss led to a reduced number of myeloid-derived cells, particularly granulocytic myeloid-derived suppressor cells (gMDSCs), but an augmented number of both CD4+ and CD8+ T cells in pancreatic cancer models." (PMID 36923542, 2023). "In addition, further characterization of the chr13q22.1 locus found a single nucleotide polymorphism (SNP) mutation in a gene desert closest to both KLF5 and KLF12 that was significantly correlated with a higher risk of pancreatic cancer." (PMID 37239940, 2023). "KLF5 had been identified as a master regulator of epithelial phenotype in pancreatic cancer." (PMID 37239940, 2023). "As such, KLF5 is pivotal during pancreatic cancer development and progression." (PMID 37239940, 2023). "Thus, at first, KLF5 plays the role of pro-tumorigenic factor, and its role switches as its presence inhibits pancreatic tumor dissemination." (PMID 37239940, 2023). "Here, we found that KLF5 could act as a positive TF with S100P and jointly participate in the malignant biological behavior of pancreatic cancer." (PMID 34654352, 2021). "Previous studies demonstrated that KLF5 is critical for pancreatic cancer progression." (PMID 34348759, 2021). "Taken together, these studies suggest KLF5 may promote cyclin D1 gene expression directly by binding to its promoter in pancreatic cancer cells." (PMID 31327760, 2019). "In addition, KLF5 inhibits expression of the tumor suppressor p16 via microRNAs, which would likely further increase the malignancy of pancreatic cancer cells." (PMID 31327760, 2019). "Moreover, we used bioinformatics analysis investigate the target genes whose transcription is affected by KLF5 in pancreatic cancer." (PMID 31327760, 2019). "To further examine the mechanisms by which KLF5 expression leads to a poorer prognosis in pancreatic cancer patients, we identified the microRNAs activated by KLF5 and their target genes and evaluated their roles in the pancreatic cancer pathway extracted in KEGG." (PMID 31327760, 2019). "Finally, flow cytometric analyses verified that KLF5 promotes G1/S progression of the cell cycle in pancreatic cancer cells." (PMID 31327760, 2019).
pancreatic cancer (continued). "Whether KLF5 binds to the Rad51 promoter to stimulate its gene expression and whether Rad51 can enhance the ability of pancreatic cancer cells to resist survival pressure from chemotherapeutic agents such as gemcitabine remain to be determined." (PMID 31327760, 2019). "Nonetheless, our results may explain in part how KLF5 affects survival time in pancreatic cancer patients." (PMID 31327760, 2019). "This experimental result may partially explain the adverse effect of KLF5 on survival time in pancreatic cancer patients." (PMID 31327760, 2019). "Our findings indicate that KLF5 is a critical oncogene in human pancreatic cancer." (PMID 31327760, 2019). "Indeed, LSD1 has been shown to physically associate with HIF1α in melanoma inhibitory activity human pancreatic carcinoma MIA PaCa-2 cells and with KLF5 in embryonic stem cells." (PMID 24886859, 2014). "We explored whether KLF5 regulates the sensitivity to PARPis in pancreatic cancer." (PMID 38433576, 2024). "Furthermore, we analyzed the TCGA dataset and found that KLF5 expression was higher in pancreatic cancer samples than that in normal samples (p = 0.0017, Student’s t-test), and high expression of KLF5 was associated with poor prognosis of patients with pancreatic cancer (p = 0.0145, log-rank test)." (PMID 34348759, 2021). "Moreover, using a TCGA dataset from 177 pancreatic cancer patients, we confirmed that higher/lower KLF5 expression is predictive of poorer/better overall and tumor-free survival, and that KLF5 is the key determinant of survival time in pancreatic cancer patients." (PMID 31327760, 2019). "However, the precise reasons why high KLF5 expression shortens the survival of pancreatic cancer patients remains unclear." (PMID 31327760, 2019). "We evaluated the relationship between KLF5, ZEB1, and HMOX1 expression in tissues from pancreatic cancer patients." (PMID 39827156, 2025). "Collectively, these results suggest that YAP1 binds to KLF5 and promotes the growth of pancreatic cancer cells, independent of TEAD and TAZ, and also indicate that ATF5 enhances the growth of pancreatic cancer cells by suppressing EGR1 expression." (PMID 40124511, 2025). "To further explore the relationship between KLFs and the prognosis of patients with pancreatic cancer, univariate Cox regression was performed, and we identified 4 significantly prognostic genes (KLF3, KLF4, KLF5, KLF6) with p < 0.05." (PMID 38773440, 2024). "We detected KLF5 protein levels in a human pancreatic duct epithelial cell line (hTERT-HPNE) and four pancreatic cancer cell lines to select suitable cell lines for further exploration." (PMID 38433576, 2024). "The combination of KLF5 inhibitors and PARP inhibitors provides a novel treatment strategy to enhance the sensitivity of BRCA1-proficient pancreatic cancer to PARP inhibitors." (PMID 38433576, 2024). "We discovered that repression of KLF5 elicited olaparib-induced DNA damage and significantly decreased the IC50 of olaparib in pancreatic cancer cells." (PMID 38433576, 2024). "As an example, the Kruppel like factor 5 (KLF5), is a potentially interesting therapeutic target in SMAD4-negative colorectal and pancreatic cancers." (PMID 37377893, 2023). "KLF5 promotes the expression of E2F1, cyclin D1, and Rad51 in pancreatic cancer and assists in the G1/S phase progression of cancer cells." (PMID 36761967, 2023). "Our findings add to the evidence that KLF5 is a potentially interesting therapeutic target in SMAD4-negative colorectal and pancreatic cancers, even if transcription factor targeting is still challenging." (PMID 37377893, 2023). "The KLF5-expressing ADM cells, called PDLP cells, have been shown to be a population of pancreatic cancer precursor cells that highly express a pro-oncogenic transcriptional regulatory network and have a strong differentiation capacity." (PMID 35965507, 2022).